METTL3 (methyltransferase 3, N6-adenosine-methyltransferase complex catalytic subunit)
Diseases named in the same sentence as METTL3 in open-access papers (continued):
Sharing a sentence is not in itself a finding about the gene and the disease.
bladder cancer (continued). "The expression of the catalytic subunit METTL3 of MTC was significantly upregulated in bladder cancer tissues and was related to the development and progression of bladder cancer patients." (PMID 34604051, 2021). "While METTL3 exhibits oncogenic functions in most cancer types, it was also reported as a tumor suppressor in RCC, bladder cancer, glioblastoma stem cell." (PMID 34531875, 2021). "Both METTL3 and FTO play crucial roles in carcinogenesis in both bladder cancer and renal cell carcinoma." (PMID 32808488, 2020). "As crucial m6A regulators, METTL3 and YTHDF2 act as oncogenes in both prostate cancer and bladder cancer." (PMID 32808488, 2020). "The carcinogenesis of METTL3 and YTHDF2 in prostate cancer and bladder cancer mainly contributes to the inhibition of antitumour genes and the promotion of oncogenes, resulting in tumour development." (PMID 32808488, 2020). "METTL3 and CDCP1 are both upregulated in bladder cancer patient samples and related to bladder cancer progression." (PMID 32765970, 2020). "In bladder cancer cells, we also found that the expression of PTEN was significantly higher in METTL3 knockdown cells, while the expression of PTEN was decreased in METTL3 overexpression cells by qRT-PCR and western blot." (PMID 31228940, 2019). "Analysis of METTL3 and CDCP1 expression in primary patient samples revealed that METTL3 and CDCP1 are strongly upregulated in the bladder cancer patient samples." (PMID 30796352, 2019). "We next performed gain-of-function assays to study the role of METTL3-m6A-CDCP1 axis in uroepithelial transformation and bladder cancer tumorigenesis." (PMID 30796352, 2019). "Inhibition of the METTL3-m6A-CDCP1 axis resulted in decreased growth and progression of chemical-transformed cells and bladder cancer cells." (PMID 30796352, 2019). "We further showed that METTL3 and CDCP1 are upregulated in the bladder cancer patient samples and the expression of METTL3 and CDCP1 is correlated with the progression status of the bladder cancers." (PMID 30796352, 2019). "Overall, our data support the oncogenic function of METTL3-m6A-CDCP1 axis in promoting the in vitro and in vivo bladder cancer progression." (PMID 30796352, 2019). "Based on the preferential m6A recognition by YTHDF1, METTL3 also facilitates translation of oncogene CDCP1, which plays a pivotal role in bladder cancer progression." (PMID 31921664, 2019). "Most importantly, the expression of METTL3 and CDCP1 is correlated with the progression status of the bladder cancers, further supporting the role of METTL3-mediated m6A pathway in bladder cancer oncogenesis." (PMID 30796352, 2019). "Most importantly, METTL3-m6A-CDCP1 axis has synergistic effect with chemical carcinogens in promoting malignant transformation of uroepithelial cells and bladder cancer tumorigenesis in vitro and in vivo." (PMID 30796352, 2019). "On the other hand, depletion of METTL3 in the transformed MC-SV-HUC-1 cells and bladder cancer T24 cells resulted in decreased level of CDCP1 protein but not the mRNA." (PMID 30796352, 2019). "driverMAPS identified the genes METTL3 and METTL14 as driver genes in the cohorts BLCA (bladder cancer) and UCEC (uterine cancer), respectively." (PMID 31363082, 2019). "There has been some research on the function of METTL3 and METTL14 in bladder cancer." (PMID 40133252, 2025). "Our data suggests that targeting METTL3/ALKBH5 and their downstream genes SLC3A2/SLC7A5 may be a potential therapeutic strategy for bladder cancer." (PMID 38267663, 2024). "During the malignant transformation, dysregulation of METTL3/ALKBH5 induced the up-regulation of m6A levels on SLC3A2/SLC7A5 mRNA in cells, which promoted translation and expression of SLC3A2/SLC7A5, and thus accelerated bladder cancer growth and metastasis." (PMID 38267663, 2024). "For example, m6A writer METTL3 could stimulate stemness of GBM, bladder cancer, cSCC, and osteosarcoma." (PMID 38655053, 2024).
bladder cancer (continued). "It was found in humans and animal models that METTL3, FTO, IGF2BP1, IGF2BP3, YTHDF1, YTHDF 2, ELAV-like protein 1 (ELAVL1), HNRNPA2B1 were upregulated in bladder cancer cells." (PMID 37701836, 2023). "Through m6A, METTL3 can either directly upregulate MYC expression or enhance the expression of AFF4, the transcription promoter of MYC, to regulate the expression of MYC in bladder cancer." (PMID 37996892, 2023). "Similarly, IGF2BP3 recognizes the m6A signal added by METTL3 in the 3′ UTR of BIRC5 mRNA to stabilize it, resulting in cell growth and metastasis of bladder cancer." (PMID 37554271, 2023). "It has been confirmed that CDCP1 was overexpressed in bladder cancer cells, mediated by m6A methyltransferase METTL3, m6A reader YTHDF1 preferentially recognizes m6A residues on CPCP1 3′-UTR and enhances the CDCP1 translation, promotes bladder cancer tumorigenesis in vitro and in vivo." (PMID 36650570, 2023). "In bladder cancer, METTL3 interacts with DGCR8, and actively promotes the maturation of pri-miR-221/222 in a m6A dependent manner, further reduces the expression of PTEN and promotes the proliferation of bladder cancer." (PMID 35022030, 2022). "Moreover, METTL3 has been shown to be oncogenic in the majority of malignancies and to be a tumor suppressor in RCC, bladder cancer, and glioblastoma stem cell." (PMID 36620557, 2022). "METTL3 can downregulate PTEN expression by interacting with the microprocessor protein DGCR8 and positively regulating pri-miR221/222 processing in an m6A-dependent manner, thus exerting oncogenic effects in bladder cancer." (PMID 36008936, 2022). "Global RNA m6A abundance and the expression of METTL3 was higher in CSCs than those in non-CSCs of bladder cancer cells." (PMID 34805173, 2021). "Moreover, as demonstrated in bladder cancer and CRC, the oncogenic role of METTL3 substantially relied on the degradation of tumor suppressor mRNAs targeted by miRNAs." (PMID 34722298, 2021). "METTL3 regulated the m6A modification and expression of AFF4, which bound to the promoter regions and sustained the transcription of Sox2 and MYC, to promote self-renewal of bladder cancer CSCs." (PMID 34805173, 2021). "Future studies could highlight the broad potential of targeting METTL3 and YTHDF2 for both prostate cancer and bladder cancer." (PMID 32808488, 2020). "Yang et al34 showed that METTL3 and ALKBH5 regulated m6A modification of the 3′‐UTR of the oncogene CDCP1 mRNA and that YTHDF1 recognized m6A modification to promote CDCP1 translation in bladder cancer." (PMID 32808488, 2020). "Here, we show that global RNA m6A abundance and the expression of m6A-forming enzyme METTL3 are higher in BCSCs than those in non-CSCs of bladder cancer (BCa) cells." (PMID 32676121, 2020). "METTL3 can actively regulate pri-miR221/222 in an m6A-dependent manner by interacting with DGCR8, a micro-processor protein that promotes the processing of pri-miR221/222 into mature miR221/222 in bladder cancer." (PMID 32765970, 2020). "Small‐molecule METTL3 and YTHDF2 inhibitors could be designed and synthetised to examine the antitumour effects and safety in both prostate cancer and bladder cancer." (PMID 32808488, 2020). "Our data identified METTL3-m6A-CDCP1 axis as a downstream target during chemical-induced transformation of uroepithelial cells; therefore, we evaluated the clinical relevance of METTL3-m6A-CDCP1 oncogenic signaling axis in bladder cancer with patient samples." (PMID 30796352, 2019). "Moreover, the expression levels of METTL3 and CDCP1 are further elevated in the muscle-invasive bladder cancer samples." (PMID 30796352, 2019). "All these results implied that METTL3 could affect pri-miRNAs processing by regulating the recognition and binding of DGCR8 to pri-miRNAs in bladder cancer." (PMID 31228940, 2019).
bladder cancer (continued). "We confirmed the oncogenic role of METTL3 in bladder cancer by accelerating the maturation of pri-miR221/222, resulting in the reduction of PTEN, which ultimately leads to the proliferation of bladder cancer." (PMID 31228940, 2019). "METTL3 enhances mRNA translation, while depletion of METTL3 selectively inhibits mRNAs translation in 5′UTR and reduces AFF4 and MYC translation in bladder cancer but increase that of zinc finger protein 750 and fibroblast growth factor 14 in nasopharyngeal carcinoma." (PMID 31142332, 2019). "Therefore, we further studied the function of METTL3-m6A-CDCP1 axis in the growth and progression of chemical-transformed uroepithelial cells and bladder cancer cells." (PMID 30796352, 2019). "Further investigation revealed that METTL3/miR-146a-5p/NUMB/NOTCH2 signaling was positively correlated with recurrence, metastasis, and survival in bladder cancer patients, indicating that MLT sheds new light on therapeutic targets for recurrent bladder cancer treatment." (PMID 38017537, 2023). "In contrast, up- or down-regulation of METTL3 in bladder cancer cells can enhance or inhibit the transcriptions and protein expression of TEK and VEGF-A, which are components of the PI3K/AKT pathway respectively, thereby affecting the angiogenesis of bladder cancer via RNA methylation." (PMID 38053093, 2023). "To validate this hypothesis, we first performed gene‐specific m6A methylated RIP qRT‐PCR analysis in bladder cancer cells transfected with or without METTL3 siRNA." (PMID 37313656, 2023). "Furthermore, METTL3 could regulate the expression of the TEK and VEGFA genes to promote angiogenesis and exacerbate bladder cancer progression." (PMID 36246403, 2022). "Moreover, METTL3 has been highlighted to augment the m6A modification in 3’-untranslated region (3'-UTR) of CUB domain containing protein 1 (CDCP1) mRNA, which is positively correlated with the malignancy status of bladder cancer." (PMID 33882457, 2021). "Another previous study corroborated our findings, which revealed that both METTL3 and CDCP1 were robustly expressed in bladder cancer, and also that the suppression of the METTL3-m6A-CDCP1 axis could restrict the bladder cancer growth and tumorigenesis both in vitro and in vivo." (PMID 33882457, 2021). "The waterfall plot showed that KIAA1429 and METTL3 presented with the highest mutation frequency, mainly for missense mutations, nonsense mutations, and multiple hits, whereas METTL16 did not present as having any mutation in bladder cancer samples." (PMID 34733275, 2021). "Similarly, Jin et al35 found that METTL3 and ALKBH5 regulated the m6A modification of the 3′‐UTR of the oncogene ITGA6 mRNA and that YTHDF1/3 recognized m6A modification to promote ITGA6 translation in bladder cancer." (PMID 32808488, 2020). "However, unlike the expression pattern in prostate cancer, bladder cancer and most other types of tumours, METTL3 seems to be down‐regulated in renal cell carcinoma." (PMID 32808488, 2020). "Similarly, in our previous study, we also found that the expression of METTL3 and YTHDF2 was up‐regulated in bladder cancer and showed that METTL3 inhibited the expression of SETD7 and KLF4 in an m6A‐YTHDF2‐dependent manner to further promote the proliferation and metastasis of bladder cancer." (PMID 32808488, 2020). "Together, these results suggested METTL3 may not directly regulate PTEN mRNA in bladder cancer." (PMID 31228940, 2019). "Results suggested that METTL3 may not directly regulate PTEN mRNA in bladder cancer." (PMID 31228940, 2019). "And we demonstrated that METTL3 could downregulate PTEN expression by interacting with the microprocessor protein DGCR8 and positively modulating the pri-miR221/222 process in an m6A-dependent manner, which may provide a prognostic and/or therapeutically target for the treatment of bladder cancer." (PMID 31228940, 2019).
bladder cancer (continued). "However, at the level of its mRNA, the prognostic analysis of METTL3 from tumor samples with detailed clinical information which were downloaded from TCGA database showed a trend of adverse prognosis in both METTL3 and bladder cancer, but it had no statistical significance." (PMID 31228940, 2019). "Immunohistochemistry (IHC) staining of bladder cancer patient tumor microarray revealed that both METTL3 and CDCP1 are moderately or highly expressed in most of the bladder cancer samples, whereas their expression are weak or not detectable in the majority of the paratumor controls." (PMID 30796352, 2019). "Determination of METTL3 and CDCP1 expression in human cystitis and bladder cancer tissues revealed that METTL3 and CDCP1 expressions are weak or not detectable in majority of the cystitis samples, although the METTL3 and CDCP1 are upregulated in the non-muscle-invasive bladder cancer samples." (PMID 30796352, 2019). "Furthermore, we found that METTL3 and PTEN were negative correlated in bladder cancer patients’ tissues." (PMID 31228940, 2019).
glioblastoma (166 papers, 2017 to 2025). The most malignant astrocytic tumor (WHO grade IV). "Its dysregulation via altered METTL3 or FTO expression is linked to glioblastoma, leukemia, and metabolic diseases." (PMID 40870000, 2025). "Dysregulation of m6A is implicated in several diseases: METTL3 overexpression in glioblastoma promotes tumorigenicity by stabilizing oncogenic transcripts, while FTO upregulation contributes to obesity and chemoresistance in leukemia." (PMID 40870000, 2025). "m6A is a critical regulator in glioblastoma and loss of METTL3 is beneficial to radiosensitivity of disease cells." (PMID 38205931, 2024). "The m6A modification has been implicated in RNA editing in glioblastoma, with METTL3 altering A-to-I and C-to-U events via the differential regulation of RNA editing enzymes ADAR and APOBEC3A." (PMID 37444417, 2023). "Another publication confirmed the METTL3-METTL14 complex’s tumorigenic function through the stabilization of mRNAs encoding splicing factors in glioblastoma." (PMID 37919739, 2023). "On the contrary, another study argued that METTL3 plays an oncogenic role in glioblastoma via methylating 3′-UTR of SOX2 mRNA, which encodes transcription factors enabling the regain of stem-like properties and efficient DNA repair." (PMID 31921664, 2019). "METTL3 is upregulated in glioblastoma and associated with poor prognosis." (PMID 41321637, 2025). "METTL3 was also found to be highly expressed in GBM and associated with maintenance of Glioblastoma Stem Cells (GSCs) versus dedifferentiation, exhibiting GBM associated oncogenic effects." (PMID 38711100, 2024). "METTL3 knockout significantly reduced the colony formation capacity and cell viability in glioblastoma cell lines (U87-MG, U251) and primary glioma cells (GBM85)." (PMID 41321637, 2025). "In glioblastoma (GBM) stem cells, METTL3 and YTHDF2 have been implicated in Yin Yang 1 (YY1)-mediated IFN-β signaling and antigen presentation through m6A methylation, reducing Treg cell infiltration and improving the efficacy of immune checkpoint therapy." (PMID 39987091, 2025). "The expression of METTL3 was upregulated in the TMZ-resistant GBM METTL3 knockdown promotes temozolomide sensitivity of glioblastoma cells." (PMID 41321637, 2025). "For example, reducing the expression of METTL3 or METTL14 has been shown to increase glioblastoma cell proliferation and self-renewal, while elevated levels of METTL3 have inhibitory effects." (PMID 41301778, 2025). "Previous studies have shown that RNA methylation by the m6A complex induced RNA editing, by increasing ADAR1 levels in response to IFN stimulation, and METTL3 was found to increase protein levels of ADAR1 in glioblastoma." (PMID 41282185, 2025). "METTL3-mediated m6A methylation of GPX4 prevents ferroptosis in Glioblastoma cells and ultimately promoting tumor progression." (PMID 40175350, 2025). "METTL3 was detected in both the cytoplasm and nucleus of glioblastoma cell lines U87-MG, U251, A172, and U373, whereas USP25 was almost exclusively detected in the cytoplasm." (PMID 41321637, 2025). "Previous studies have reported a tumor-suppressive role of METTL3 in glioblastoma stem cells, endometrial cancer, and ocular melanoma 33-35." (PMID 41208889, 2025). "For example, METTL3 knockdown in glioblastoma reduces m6A levels but upregulates alternative splicing factors to maintain transcript homeostasis." (PMID 40847370, 2025). "In glioblastoma, METTL3 modified and promoted the expression of genes involved in histone modifications in an m6A-dependent manner." (PMID 38503745, 2024). "A study showed that the METTL3/14 complex silencing significantly improved the glioblastoma stem cells (GSCs)-related self-renewal properties, resultantly leading to tumor progression." (PMID 38355684, 2024). "In temozolomide-resistant glioblastoma stem-like cells, m6A modification significantly increases, and temozolomide treatment induces upregulation of METTL3, leading to increased m6A methylation." (PMID 39473440, 2024).